IAPP (islet amyloid polypeptide)
Diseases named in the same sentence as IAPP in open-access papers (continued):
Sharing a sentence is not in itself a finding about the gene and the disease.
Alzheimer disease (74 papers, 2005 to 2026). A progressive, neurodegenerative disease characterized by loss of function and death of nerve cells in several areas of the brain leading to loss of cognitive function such as memory and language. "The Bri2 protein contains a 100 residue-long BRICHOS domain attributed to a chaperone-like function and has been shown to assist folding and inhibit fibril formation of amyloid β-peptide and IAPP, associated with Alzheimer’s disease and type 2 diabetes, respectively." (PMID 41212211, 2026). "Besides, the polypeptide has been linked with Alzheimer’s disease (AD), since IAPP deposits have been found in the brains of AD patients, regardless of T2DM diagnosis." (PMID 36793056, 2023). "Additionally, rs73069071 maps in an intronic region in the islet amyloid polypeptide, IAPP, which has been previously implicated in Alzheimer’s disease (AD) etiology." (PMID 29986742, 2018). "However, other types, such as senile with normal transthyretin (ATTR), amyloidosis associated with Alzheimer's disease (Aβ), and islet amyloid polypeptide deposits (AIAPP) are very strongly associated with both old age and the aging process." (PMID 16138931, 2005). "Bri2/BRICHOs prevents amyloid formation from both IAPP (in islets) and Aβ (amyloid protein that deposits in patients with Alzheimer’s disease)." (PMID 41212211, 2026). "In patients affected by T2D, IAPP undergoes conformational changes to form highly-ordered β-sheets organized into amyloid fibers similar to those found in Alzheimer disease (AD)." (PMID 32582762, 2020). "The NLRP3 inflammasome-activating DAMPs include metabolic danger signals (i.e., cholesterol crystals, uric acid crystals, saturated fatty acids, and islet amyloid polypeptide) and amyloid-β in Alzheimer's disease." (PMID 31417575, 2019). "For example, the fibril aggregates of α-synuclein (α-Syn), islet amyloid polypeptide (IAPP), and amyloid beta (Aβ) peptide are involved in Parkinson’s disease (PD), type II diabetes (T2D), and Alzheimer’s disease (AD), respectively." (PMID 31416122, 2019). "Many polyphenols have been found to have anti-aggregation effects on IAPP as well as some other amyloidogenic peptides, such as Aβ in Alzheimer’s disease." (PMID 26763863, 2016). "IAPP and Aβ, the peptide responsible for amyloid formation in Alzheimer's disease, are particularly interesting in this regard as they are both natively unfolded in their monomeric states and share some common characteristics." (PMID 25260075, 2014). "We have recently shown that brain tissue from patients with T2D and cerebrovascular dementia or Alzheimer’s disease (AD) contains significant accumulation of the pancreatic hormone amylin (islet amyloid polypeptide)." (PMID 25149184, 2014). "IAPP is also a neuropancreatic hormone that plays a significant role in Alzheimer's disease (AD) by co-depositing with amyloid-beta (Aβ) and Tau, supporting the Type 3 Diabetes (T3D) hypothesis." (PMID 41898768, 2026). "They include prion protein involved in spongiform transmissible encephalopathies, amyloid beta-peptides in Alzheimer’s disease, tau tangles in Alzheimer’s disease, α-synuclein in Parkinson’s disease, huntingtin in Huntington’s disease, and islet amyloid polypeptide in type II diabetes." (PMID 39684527, 2024). "Accordingly, oxidized LDL (oxLDL), but also islet amyloid polypeptide (IAPP) and Alzheimer Disease beta amyloid peptides (Aβ1–42), induce Nlrp3 and Il1β gene expression, and thus the priming of this pathway in a CD36-TLR2-TLR4 heterotrimer-dependent manner in bone marrow-derived macrophages (BMDM)." (PMID 33716981, 2021). "Thus these data indicate a previously unidentified mitochondrial pool of IAPP, which is analogous to the pool of Aβ localized inside mitochondria in Alzheimer’s disease." (PMID 26191799, 2015). "Notably, IAPP has been shown to contribute to the pathophysiology of Alzheimer’s disease (AD)." (PMID 40046847, 2025).
Alzheimer disease (continued). "Under pathological conditions, the mitochondrial IAPP concentration could increase and be an important factor in inducing mitochondrial dysfunction, similar to the role of mitochondrial amyloid β-peptide in Alzheimer’s disease." (PMID 26191799, 2015). "Bri2 BRICHOS has been shown to prevent amyloid fibril formation from IAPP and Aβ in vitro and i.v. injections of BRICHOS reduced the amyloid load and gliosis in an mouse model of Alzheimer’s disease." (PMID 41212211, 2026). "Cross-interactions between amyloid-β peptide (Aβ) and islet amyloid polypeptide (IAPP), key polypeptides of Alzheimer’s disease (AD) and type 2 diabetes (T2D), have been suggested to link AD with T2D pathogenesis." (PMID 36008417, 2022). "In the present study, we show that IDN5706 disrupts APP glycosylation, and stimulates the degradation of iAPP through Atg5-dependent autophagy, with a resulting reduction in the processing of APP to CTFs, which could have beneficial effects to Alzheimer's disease." (PMID 26308941, 2015). "There are some observations that amyloid fibrils, e.g. islet amyloid polypeptides (IAPP) and Alzheimer×s amyloid-β, can trigger NLRP3 inflammasomes and in that way stimulate inflammation and enhance pathogenesis in type 2 diabetes and Alzheimer×s disease, respectively." (PMID 22411934, 2012).
amyloidosis (44 papers, 2005 to 2025). A disorder characterized by the localized or diffuse accumulation of amyloid protein in various anatomic sites. "The aggregation of human Islet Amyloid Polypeptide (hIAPP) on cell membranes is linked to amyloid diseases." (PMID 37241931, 2023). "The only pancreatic tumor associated with amyloidosis is Insulin expressing pancreatic neuroendocrine tumor, which is rarely associated with IAPP-type amyloidosis." (PMID 33579198, 2021). "We then apply this technique to determine the solvent exposure of membrane-attached N-terminus labelled amylin (h-IAPP, an amyloid associated with Type II diabetes) whose interaction with lipid bilayers is poorly understood." (PMID 34926574, 2021). "Thus, IAPP amyloidosis should be considered not only as a result, but also a cause of aggravation of T2DM symptoms." (PMID 32724729, 2020). "The misfolding and subsequent self-aggregation of intrinsically disordered proteins, such as human Islet Amyloid Polypeptide (hIAPP), on the surfaces of lipid membranes are the major molecular mechanisms leading to the progression of various amyloid diseases." (PMID 37241931, 2023). "Meanwhile, IAPP fibrils were considered to be interacted with transthyretin, which further resulted in amyloid fibrosis deposition and eventually gave rise to the decreased percentage of pancreatic β-cells." (PMID 35889910, 2022). "Increased activity of β-cells leads to the overproduction of IAPP, which in turn triggers IAPP intracellular oligomerization and the accumulation of extracellular amyloid plaques." (PMID 34574099, 2021). "Islet amyloid polypeptide (IAPP) or Aβ microinjection into zebrafish embryos can produce an AD-like animal model to study amyloidosis." (PMID 34335276, 2021). "In the form of amylin or islet amyloid polypeptide accumulation, amyloidosis is also observed in the pancreas under diabetic condition." (PMID 33379163, 2020). "The observation, according to which proteins from amyloid deposits such as Aβ-peptide, IAPP, tau, prions, and transthyretin can be glycated, indicates a direct relationship between protein glycation and amyloidosis." (PMID 32503113, 2020). "While fibrosis and lipomatosis affect mostly the interstitial tissue and their effects on the cells are secondary, the IAPP amyloidosis takes place in the isles of Langerhans, damaging the endocrine parenchyma and its secretion directly." (PMID 32724729, 2020). "Human Amylin, also known as human islet amyloid polypeptide (hIAPP), is the major factor for categorizing Type II diabetes as an amyloid disease." (PMID 31919432, 2020). "Evidences suggest that transthyretin (TTR), a plasma protein associated with transthyretin amyloidosis or familial polyneuropathy (FAP) interacts with heterologous amyloid proteins including amyloid beta and islet amyloid polypeptide." (PMID 29593496, 2018). "Again, IAPP inhibition is also proposed via an indirect mechanism, whereby a reduction in an individual’s insulin requirements will in turn reduce the production of IAPP and therefore amyloidosis." (PMID 28754022, 2017). "Systematic molecular dynamics simulations further provided molecular and structural details for the observed differential effects of proteins on IAPP amyloidosis." (PMID 28550295, 2017). "Although the basic processing of ProIAPP into mature IAPP is well defined, much remains to be learned about both the contribution of ProIAPP to amyloidogenecity, and the possibility of further modifications to both ProIAPP and IAPP that could modulate amyloidosis and prevent beta-cell loss." (PMID 26840340, 2016). "The results provide important information about the nature of toxic IAPP oligomers, their unique properties and the common features they share with toxic entities produced in other amyloidosis diseases." (PMID 27213520, 2016). "Amylin or islet amyloid polypeptide (IAPP) is a 37-amino acid peptide first isolated from amyloid-rich pancreatic extracts of type-2 diabetic patients." (PMID 23966942, 2013).
amyloidosis (continued). "IAPP amyloidosis was first observed in 1901 as 'hyaline degeneration of the isles of Langerhans' and a connection between T2DM and this condition was suggested, but it was not until 1987 that the structure of the substance was clarified and further described in other diabetic patients." (PMID 32724729, 2020). "We have applied ThT fluorescence assay, CD spectroscopy, TEM imaging, cell viability assay and atomistic DMD simulations to examine the effects of protein binding on IAPP amyloidosis, including IAPP aggregation kinetics and dynamics, fibril remodelling and cytotoxicity." (PMID 28550295, 2017). "Based on our findings that BACE2 proteolytically cleaves hIAPP at residues F15 and F23, one may predict BACE2 therapy as means for disrupting both IAPP-IAPP and IAPP-Aβ interactions at a molecular level and, in so doing impede homo- and hetero-amyloidosis." (PMID 26840340, 2016). "Studies suggest that aberrant or unprocessed ProIAPP may also contribute to IAPP-based amyloidosis." (PMID 26840340, 2016). "It is important to remember that amyloids are also the signature of systemic amyloidoses, a group of fatal diseases in which organs other than the CNS accumulate ordered aggregates of proteins, including transthyretin, immunoglobulin light chains and islet amyloid polypeptide." (PMID 25437612, 2014). "While the IAPP of humans, non-human primates, including cats and the degu, are also known to develop islet amyloid, it has been discovered that rat amylin (rIAPP) does not." (PMID 39072260, 2024). "Previously, we and others have shown that IAPP is present in Aβ deposits in the human brain, and proximity ligation assay (PLA) was used to confirm co-localization of Aβ and IAPP in amyloid deposits in both cortex and blood vessel walls of AD patients." (PMID 36793785, 2023). "Against thisbackground, we questioned whether IAPP-amyloid could induce TTR-fibrilformation, and also whether deposition of TTR-amyloid in the pancreas leads toislet amyloidosis, either by deposition of fibrils from TTR or from IAPP." (PMID 18825272, 2008). "The islet amyloid polypeptide (IAPP), as the major amyloid component, could undergo LLPS by triggering deleterious aggregation and formation of islet amyloid deposits, which resulted in the pancreatic β-cell dysfunction and was at the heart of the pathology of T2DM." (PMID 36230986, 2022). "Islet IAPP levels were decreased 3-fold while islet amyloid deposition was not investigated." (PMID 32131431, 2020). "Due to the lack of amyloidosis in rodents, the possible effect of a BACE2 inhibitor on IAPP would be undetectable in this model." (PMID 26840340, 2016).
Insulin resistance (42 papers, 2008 to 2026). Increased resistance towards insulin, that is, diminished effectiveness of insulin in reducing blood glucose levels. "Insulin resistance is associated with the overexpression of islet amyloid polypeptide (IAPP), which can aggregate both intra- and extracellularly into giant insoluble amyloid fibrils and small soluble amyloid aggregates." (PMID 39199339, 2024). "Participants with prediabetes who consumed 180 mg of curcumin daily had significantly reduced GSK3β and IAPP in serum samples after 12 weeks compared with placebo groups, reducing insulin resistance and the risk of developing AD and DM." (PMID 36909158, 2023). "NLRP3 activation has been described in response to hyperglycemia, saturated fatty acids, and islet amyloid polypeptide and is linked to glucose intolerance, insulin resistance, and beta-cell death." (PMID 37400850, 2023). "In vulnerable individuals, insulin resistance induces a progressive loss of insulin secretion with islet pathology revealing a partial deficit of beta cells and islet amyloid derived from islet amyloid polypeptide (IAPP)." (PMID 36814640, 2023). "There is extensive evidence linking dysfunction or loss of β-cells with reduced secretion of insulin and development of insulin resistance which is linked to IAPP amyloid formation." (PMID 35475576, 2022). "The subsequent release of cytokines can induce insulin resistance in β-cells and secretion of IL-1β has been linked to IAPP aggregation." (PMID 35475576, 2022). "Elevated serum levels of IAPP is a pathological hallmark of insulin resistance and correlates with AD diagnosis." (PMID 32283762, 2020). "The aim of this study was to determine if dietary supplementation with curcumin reduce plasma levels of peptides, GSK-3β and IAPP that are implicated in the insulin resistance in people at a high risk of developing T2D." (PMID 32283762, 2020). "Recent studies have also indicated that the high plasma levels of IAPP is a pathological hallmark of insulin resistance and correlates with AD diagnosis and brain structure." (PMID 32283762, 2020). "In a 12-week randomized controlled trial, participants with prediabetes who consumed 180 mg of curcumin daily had significantly reduced GSK3β and IAPP in serum samples after 12 weeks compared with placebo groups, reducing insulin resistance and the risk of developing AD and DM." (PMID 36909158, 2023). "IAPP and tau may interact by cross-seeding, providing a potential new mechanistic explanation for the higher risk of AD in individuals affected by insulin resistance or T2DM." (PMID 35093145, 2022). "In addition, prion-like aggregates of the islet amyloid polypeptide (IAPP) in the islets of Langerhans were proposed to play important roles in causing β-cell dysfunction and loss resulting in insulin resistance and hyperglycemia." (PMID 35163973, 2022). "Overproductionof IAPP in insulin resistance may occur due to common transcription regulatory elements inthe promoter regions of the IAPP and insulin genes, and this might underly theenhanced amyloid formation in DM2." (PMID 18497871, 2008). "The alternative and conventional hypothesis explains development of T2D with increasing insulin resistance causing exhaustion of pancreatic ß-cells due to over-secretion of insulin, and thus IAPP, too, resulting in subsequent IAPP aggregation and fibril deposition in the pancreas." (PMID 39174611, 2024). "IAPP and α‐synuclein, as well as Aβ and tau, have been found to be colocalized in pancreatic β cells in patients with synucleinopathies, which may underlie the appearance of insulin resistance in non‐T2DM AD, PD, or dementia with Lewy bodies patients." (PMID 35699244, 2022). "Additional stressors, such as hyperglycemia and insulin resistance are known to exacerbate amyloid formation by increasing IAPP production." (PMID 39859479, 2025).
Insulin resistance (continued). "Unfortunately, there are few studies of anti-diabetic therapy targeting other mechanisms, such as the insulin resistance-related decrease in dopamine turnover and the cross-talk between IAPP and α-synuclein." (PMID 39847072, 2025). "Dietary supplementation with curcumin has shown that it reduces circulating levels of islet amyloid polypeptide (IAPP) and GSK3β, significantly alleviating insulin resistance." (PMID 39399315, 2024). "Further correlation analyses of values at baseline demonstrated correlations between IAPP levels and various metabolic and inflammatory plasma markers, in particular insulin, insulin resistance, CRP, and GGT." (PMID 39062913, 2024). "Insulin resistance leads to a compensatory increase in the synthesis and secretion of insulin by the beta cells of the islets of Langerhans and, accordingly, IAPP." (PMID 37833898, 2023). "Investigations performed on AD patients revealed a correlation between insulin resistance and increased levels of Aβ and amylin (islet amyloid polypeptide, IAPP)." (PMID 34360906, 2021). "IAPP can also induce peripheral insulin resistance by antagonising insulin activity, further linking to the overexpression of glycogen synthase kinase-3 (GSK-3)." (PMID 32283762, 2020). "In T2DM, IAPP is overproduced together with insulin in pancreatic islet β cells in order to compensate for insulin resistance, which promotes formation of islet amyloid deposits." (PMID 32604774, 2020). "The primary finding of this study is that oral supplementation with curcumin (180 mg per day) for 12 weeks reduces the circulating levels of peptides that are implicated in insulin resistance, namelt GSK-3β and IAPP." (PMID 32283762, 2020). "In this study, we provided novel insights on the efficacy of curcumin in insulin resistance by providing evidence on regulation of key peptides such as GSK-3β and IAPP, which play an important role in insulin resistance." (PMID 32283762, 2020). "Insulin resistance leads to increased production of insulin to compensate for its impaired signaling, which is accompanied by increased production of IAPP." (PMID 32604774, 2020). "Insulin resistance and IAPP expression induced by fatty acids aggravated the pancreatic islet cell apoptosis in vivo." (PMID 29523142, 2018). "Islet amyloid polypeptide, the concentrations of which are elevated in PC patients with DM, appears to be responsible for the insulin resistance." (PMID 28445955, 2017). "This lower frequencymight be due to differences in the genetic background and/or the composition ofthe diet, influencing insulin resistance and IAPP expression." (PMID 18497871, 2008). "Insulin resistance and hyperglycaemia may contribute to the formation of amyloid in human islets in vivo by the increased production of IAPP from the beta cells." (PMID 41212211, 2026). "Additionally, PDAC-associated systemic inflammation and tumor-derived factors, such as adrenomedullin and islet amyloid polypeptide, can induce insulin resistance, further contributing to hyperglycemia." (PMID 39405289, 2024). "However, it is well-established that inflammation induces insulin resistance, which leads to an increased co-secretion of insulin and IAPP." (PMID 39062913, 2024). "Insulin resistance promotes the oxidative stress generation and proinflammatory cytokines secretion in beta-cells inducing mitochondrial dysfunction and accumulation of protein aggregates, including human islet amyloid polypeptide (hIAPP)." (PMID 37342358, 2023). "In addition, obesity sensitizes neurons to pain-inducing stimuli, and hyperglycemia, as well as obesity-related insulin resistance, increases IAPP transcript levels and IAPP biosynthesis in pancreatic islet β cells." (PMID 36917177, 2023).